IL4 (interleukin 4)
Diseases named in the same sentence as IL4 in open-access papers (continued):
Sharing a sentence is not in itself a finding about the gene and the disease.
asthma (continued). "Dupilumab, the focus of this review, is a novel biologic agent that blocks IL-4 and IL-13 cytokine signaling, which is central to T2 inflammation in asthma." (PMID 40843371, 2025). "For instance, during acute asthma attacks, IL-4 can significantly increase the aggregation and activation of inflammatory cells in the airways, thereby inducing and aggravating acute asthma episodes." (PMID 39831768, 2025). "This strategy is particularly promising for T2-high asthma, a subtype driven by heightened sensitivity to Th2 cytokines like IL-4 and IL-13." (PMID 40806756, 2025). "The classical asthma immune response is primarily driven by allergen-specific Th2 and type 2 innate lymphoid cells, which produce mainly IL-4, IL-5, and IL-13." (PMID 40573126, 2025). "Both asthma and CRS have implicated type 2 inflammation pathways of innate immunity, including IL-4, IL-6, IL-13, and the TSLR pathway." (PMID 41213931, 2025). "Type 2 cytokines, such as: IL-4, IL-5 and IL-13, as well as IL-8 play a significant role in asthma development." (PMID 40389545, 2025). "In asthma, histone acetylation changes and methylation alterations in genes such as IL-4 and FOXP3 promote Th2-dominated immune responses and airway hyperreactivity." (PMID 41020825, 2025). "In experimental studies, it was found that the IL-4 and IL-13 functions were positively correlated at the molecular level and in asthma." (PMID 40953067, 2025). "Th2-high asthma, one of the most well-characterized endotypes, is driven by IL-4, IL-5, and IL-13-mediated eosinophilic inflammation, airway remodeling, and epithelial dysfunction." (PMID 40503233, 2025). "T2-high asthma is seen in around 50% of patients, who typically have eosinophilic inflammation mediated by cytokines including IL-4, IL-5, and IL-13, with enhanced levels of immunoglobulin E (IgE) often present." (PMID 41440490, 2025). "The effects of prolonged IL-4 and IL-13 stimulation on alarmin and antiviral responses were studied in BECs from healthy and asthma donors exposed to a combination of IL-4 and IL-13 for 10 days prior to infection with RV." (PMID 40370530, 2025). "All these immune cells release a specific set of cytokines, predominantly IL-4, IL-5, and IL-13, playing vital roles in key features of asthma pathology." (PMID 40337626, 2025). "ICGAC suppressed IL-4 and other asthma-related cytokines, thus reducing IgE production by B cells and alleviating asthma symptoms by lowering airway responsiveness." (PMID 40430003, 2025). "Functional annotation using gene set enrichment analysis (GSEA) showed that upregulation of Th2 specific pathways including those related to asthma, IL-4/IL-17 signaling, and cytokine-cytokine receptor interactions." (PMID 40131363, 2025). "Th2 cells secrete cytokines such as IL-4, IL-5, and IL-13, which promote IgE production and eosinophil infiltration, thereby triggering asthma symptoms." (PMID 40417314, 2025). "From a physiological mechanism perspective, estrogen exerts a direct protective effect on asthma by inhibiting Th2-type inflammatory responses (e.g., reducing the release of IL-4, IL-5, and IL-13) and lowering airway hyperresponsiveness." (PMID 41244254, 2025). "Th2 cells produce IL-4 and IL-13, key cytokines in asthma inflammation, while Th17 cells produce IL-17, which is closely related to the pathogenesis of neutrophilic and eosinophilic asthma." (PMID 41293155, 2025). "Type‐2‐high asthma has been characterized by elevated airway or blood eosinophils and high levels of Th2 cytokines IL‐4, IL‐5 and IL‐13 in the airways produced by both T cells and ILCs." (PMID 40105091, 2025). "Among the strains with higher interferon-γ (IFN-γ)/IL-4 ratio was the SJL/J strain, which is widely used as an animal model for multiple sclerosis, while the well-known asthma-susceptible strain, BALB/cJ, belonged to the group of lower IFN-γ/IL-4 ratio." (PMID 40088449, 2025).
asthma (continued). "Compared with control mice, IL-4, IL-5, and IL-13 concentrations were significantly increased in mice with asthma." (PMID 40343297, 2025). "IL-4 is a key cytokine in the induction of Type 2 helper T cells (Th2) that mediate allergy, asthma, and wound repair, and in addition, acts as an anti-inflammatory cytokine that antagonizes Type 1 (IFNγ) immune responses." (PMID 40738263, 2025). "Collectively, these findings suggest that targeting IL-4 or IL-13 individually is insufficient to achieve asthma control, highlighting the need for alternative strategies." (PMID 41145900, 2025). "These selected probiotic strains helped reduce allergic skin responses and, later, asthma by decreasing inflammation, particularly IL-4." (PMID 41155390, 2025). "All the anti–IL-5 and anti–IL-4/IL-13 therapies tested in the included studies showed beneficial effects in terms of lung function, asthma control, and reducing the rate of exacerbations." (PMID 39844912, 2025). "Studies have found that Bifidobacteria can stimulate Th1/Th2 balance, upregulate inflammatory factors such as IFN‐γ, IL‐4, and IL‐12 in the lungs, and regulate asthma attacks." (PMID 41310922, 2025). "Type-2-high asthma is characterized by elevated secretion of interleukins IL-4, IL-5, and IL-13, increased eosinophil counts, and higher total immunoglobulin E (IgE) levels." (PMID 41515904, 2025). "In asthma, several cytokines such as IL-4, IL-5, IL-13, and VEGF play key roles in disease pathogenesis by promoting airway eosinophilia, mucus overproduction, bronchial hyperresponsiveness, immunoglobulin synthesis, and angiogenesis." (PMID 40506894, 2025). "We examined the correlations of serum IL-36 levels with serum IL-6, IL-8, IL-10, IL-13, IL-17, IFN-γ, and TNF levels, except for IL-4 and IL-5 levels, which were only rarely observed in our asthma patients." (PMID 40115968, 2025). "This revealed elevated levels of the asthma-promoting cytokine IL-4 and TNFα, with TNFα levels returning to baseline following nociceptor ablation." (PMID 39229121, 2025). "The role of the NLRP3 inflammasome in asthma is not limited to cytokine production; it also influences macrophage polarization, particularly promoting the M2 phenotype through IL4 upregulation, which contributes to the chronic inflammation observed in asthma." (PMID 40598285, 2025). "IL-4 and IL-13 play crucial roles in many aspects of airway changes in asthma, whereas IL-5 supports the development and amplification of eosinophilic inflammation and the induction of airway remodeling." (PMID 39962262, 2025). "Th2 cells subsequently produce the characteristic cytokines of type 2 inflammation—IL-4; IL-5; and IL-13—which coordinate the allergic and eosinophilic responses in asthma." (PMID 40564060, 2025). "Biologic therapies targeting cytokines IL-4, IL-5, and IL-13 have been shown to provide benefits to asthmatic patients over currently existing asthma treatments." (PMID 39844912, 2025). "It is an extracellular matrix protein upregulated in response to IL-4 and IL-13, signaling-key drivers of type 2 (T2) inflammation characterizing a major asthma endotype." (PMID 41374409, 2025). "Both IL-4 and IL-13 can contribute to many of the observed airway changes seen in asthma, including airway hyperreactivity, goblet cell hyperplasia, mucous production, smooth muscle proliferation, and subepithelial basement membrane thickening." (PMID 39586024, 2025). "After mast cell and/or basophil meets an allergen, leukotriene D4 and PGE2 are produced within 30 min, and within several hours, TNF-α and IL-4 are released in various situations such as asthma, allergic rhinitis, and atopic dermatitis." (PMID 40323927, 2025). "While T2 inflammation, driven by cytokines like IL-4, IL-5, and IL-13, is common in childhood asthma, non-T2 asthma, characterized by neutrophilic or pauci-granulocytic patterns, also exists." (PMID 40486460, 2025).
asthma (continued). "Due to its blockage of the cytokine-induced damage, dupilumab is commonly used to treat diseases that utilize the IL-4 and IL-13 pathway, including asthma, atopic dermatitis, chronic sinusitis with nasal polyps, and eosinophilic esophagitis." (PMID 40861695, 2025). "Our study on T2 cytokines' effects on BECs reveals that asthma BECs have an increased inflammatory response to IL-4 and IL-13." (PMID 40370530, 2025). "A systems pharmacology approach has identified the capacity of baicalin to target 48 asthma-related genes such as IFNγ, IL4, IL5, IL10, IL13, and TNFα and signaling pathways, reinforcing its polypharmacological properties." (PMID 40598285, 2025). "TH2 cytokines mediate key asthma characteristics: IL-5 for tissue eosinophilia, IL-13 for bronchial hyperresponsiveness, and IL-4 plus IL-13 for goblet cell metaplasia." (PMID 40732309, 2025). "Dupilumab is a monoclonal antibody targeting the interleukin-4 (IL-4) and interleukin-13 (IL-13) receptor complex and is used for the treatment of atopic dermatitis (AD), severe asthma, chronic rhinosinusitis with nasal polyps, and prurigo nodularis (PN)." (PMID 40322378, 2025). "For instance, necrotizing pneumonia similar to our case has been reported in a 61-year-old man with severe asthma receiving dupilumab, an anti-IL-4/IL-13 monoclonal antibody, who developed bilateral cavitary lesions confirmed on computed tomography." (PMID 41567916, 2025). "Severe asthma pathophysiology is essentially Type 2 (T2) inflammation-dominated, with the major cytokines, interleukin-4 (IL-4), IL-5, and IL-13 involved." (PMID 40283665, 2025). "As reported, IL-4, IL-5, and IL-13 are proinflammatory cytokines; eotaxin is a pivotal chemokine crucial for eosinophil homing to the lungs of asthma patients; and CCL4, CCL5, MCP-1, and GM-CSF recruit macrophages." (PMID 40050290, 2025). "Recent studies have provided substantial evidence that Th2 cell-related cytokines, such as IL-4, IL-5 and IL-13, play a pivotal role in the development and severity of asthma." (PMID 40323927, 2025). "Given its central role in asthma pathophysiology, IL-4 has been targeted by biologic therapies aiming to mitigate its effects." (PMID 40564060, 2025). "IL-4 released from allergen-bound Th2 cell stimulates the release of IL-4, IL-5, and IL-13, promotes IgE production from B cells, and accelerates inflammation in asthma patients." (PMID 40323927, 2025). "The data affirm the safety and efficacy of IL-4/IL-13 blockade across a broad age range, supporting dupilumab’s role as a targeted therapy for pediatric patients with T2-driven asthma." (PMID 40843371, 2025). "Asthma, marked by inflammation driven by type 2 helper T (Th2) cells and cytokines like IL-4, IL-5, and IL-13, also involves Th17 cells and IL-17 in more severe instances." (PMID 40661126, 2025). "When various biological agents relate to IgE, thymic stromal lymphopoietin (TSLP) and Th2 cytokines (IL-4, IL-5, IL-13) are added to intensive controller medications; these agents are somewhat effective for a subgroup of patients with severe asthma." (PMID 40001485, 2025). "Asthma is characterized by chronic airway inflammation, and interleukins like IL‐4 and IL‐8 are involved in the inflammatory and immune responses." (PMID 41185941, 2025). "Decreased levels of IL-4 in asthma patients have been reported before, despite it being a regulator of IgE synthesis in vitro." (PMID 40725075, 2025). "IL-4 and IL-13, along with their receptors, have therefore become targets for add-on biological therapy in T2high asthma patients." (PMID 41145900, 2025). "These biomarkers reflect the underlying immunopathology driven by cytokines such as interleukin-4 (IL-4), interleukin-5 (IL-5), and interleukin-13 (IL-13), which are key therapeutic targets in modern asthma management." (PMID 41149833, 2025). "Another compound, altrakincept, which is an inhaled humanized recombinant IL-4R, was used to block endogenous IL-4 in patients with asthma." (PMID 41145900, 2025).
asthma (continued). "Th2-high asthma, characterized by elevated levels of IL-4, IL-5, and IL-13 alongside eosinophilic infiltration, typically demonstrates favorable responses to corticosteroids and specific biologics." (PMID 41394843, 2025). "PF-07275315 (Tilrekimig) is a trispecific antibody targeting TSLP, IL-4, and IL-13 currently in phase 2 clinical development for the treatment of asthma (NCT06977581) and atopic dermatitis (NCT05995964)." (PMID 41409758, 2025). "Several genes within the cytokine gene cluster on chromosome 5, specifically IL3, IL4, CSF2, TSLP, IL5, RAD50, and IL13, are recognized as potential asthma susceptibility genes due to their roles in inflammatory regulation among sensitized asthma patients." (PMID 41001556, 2025). "It attenuated ILC2-dependent airway inflammation by suppressing basophils-derived IL-4 production and modulating ILC2s activation in a papain-induced asthma murine model." (PMID 40236701, 2025). "Periostin expression is induced in airway epithelial cells by Th2 cytokines, particularly interleukin (IL)-4 and IL-13, pivotal mediators of type 2 inflammation in asthma." (PMID 41374409, 2025). "More importantly, ILC2s were suggested one of the major sources of steroid-resistant IL-4 and IL-13 transcripts in mice models of steroid-resistant asthma exacerbation." (PMID 40236701, 2025). "Among these, Type 2-high (Th2-high) asthma is the most well-characterized in both children and adults, driven by IL-4/IL-5/IL-13-mediated eosinophilic inflammation and elevated fractional exhaled nitric oxide (FeNO)." (PMID 40503233, 2025). "The inflammation assay of allergy after the dust storm in Al‐Anbar showed that the level of IL‐4 in patients with asthma was significantly greater than before the dust storm (p < 0.0001)." (PMID 41185941, 2025). "While multiple endotypes of asthma have been described, the most common is allergic asthma, characterized by the production of the type 2 cytokines IL-4, IL-5, and IL-13 following allergen exposure." (PMID 41256356, 2025). "For instance, blocking the action of IL-4, IL-5, and IL-13 with monoclonal antibodies has shown a reduction in airway inflammation and an improvement in asthma symptoms." (PMID 40370530, 2025). "Dupilumab (DUP) is a monoclonal antibody that inhibits interleukin IL-4 and IL-13 signaling and is approved for type 2 Inflammatory Disease such as asthma, chronic rhinosinusitis with nasal polyposis and atopic dermatitis." (PMID 39798025, 2025). "In contrast, elevated FeNO in asthma reflects eosinophils, which release toxic potent inflammatory cytokines such as IL-4, IL-5, and IL-13 that induce airway alterations termed sensitization and swelling." (PMID 40662069, 2025). "Numerous studies examining the effectiveness of anti-IL-4 therapeutics in the management of asthma have produced contradictory findings." (PMID 40136649, 2025). "This made T cells hypersensitive to IL-4, promoting Th2/Th9 development and worsening asthma inflammation and pathology." (PMID 40893770, 2025). "In asthma patients, IL-4 and IL-5 are secreted, which generate eosinophils and induce airway inflammation and airway remodeling." (PMID 40958130, 2025). "Asthma is triggered by a variety of cytokines (such as IL-4, IL-5, IFN-γ, etc.)and inflammatory medium chronic inflammatory disease of the airway." (PMID 40563981, 2025). "Despite the efficacy of inhaled corticosteroids and biologics targeting IL-4 or IL-5 in many asthma patients, a significant subset still experiences poor asthma control, highlighting the need for complementary therapeutic approaches." (PMID 40430465, 2025). "Salidroside has also been reported to alleviate inflammatory cell infiltration in OVA-induced asthma mouse models, suppress IL-4, IL-5, and IL-13 expression, and reduce phosphorylation of Akt and GSK3β." (PMID 40490797, 2025). "Type 2 cytokines (IL-4, IL-5, and IL-13), and IL-6 promote airway inflammation and tissue damage in asthma patients." (PMID 40933988, 2025).
asthma (continued). "In type 2-high asthma, chronic airway inflammation is driven by Th2 cells and type 2 innate lymphoid cells, mediated by type 2 cytokines (interleukin-4 (IL-4), IL-5, and IL-13)." (PMID 41181101, 2025). "As key cytokines of Th2-type inflammation, IL-4 and IL-13 play a crucial role in the pathogenesis of asthma." (PMID 40636260, 2025). "For decades asthma has been characterized as a chronic airway condition with eosinophils in the sputum and airways, driven by IL-4, IL-5 and IL-13 from type 2 CD4+ T helper cells." (PMID 40821845, 2025). "IL-4 levels in lung from OVA-induced asthma rats were significantly increased compared to controls and markedly decreased by GEB treatment." (PMID 40958130, 2025). "The inhibition of IL-4 or its receptor in mouse paradigms of allergen-sensitized asthma has been demonstrated to reduce pulmonary swelling, blood IgE concentrations, and bronchial hyperactivity to cholinergic drugs (i.e., methacholine)." (PMID 40136649, 2025). "This suggests that GEB treatment has an anti-inflammatory and anti-allergic effect by reducing the levels of IgE and the cytokines IL-4, IL-5, and IL-13 and ameliorating histopathological changes in an asthma rat model." (PMID 40958130, 2025). "Dupilumab, initially approved for atopic dermatitis and asthma, blocks IL-4 and IL-13 signaling and has shown promising results in BP, especially in severe cases or when traditional therapies fail." (PMID 41143232, 2025). "Dupilumab is an approved therapy for severe asthma, nasal polyposis and atopic dermatitis that inhibits IL-4 and IL-13 signaling by specifically targeting the shared IL-4Rα subunit of their respective receptor complexes." (PMID 40195539, 2025). "T helper 2 cells (Th2 cells) responses play a central role in asthma pathogenesis, by activating cytokines like interleukin (IL)-4, IL-5, IL-9, and IL-13, which promote eosinophil infiltration into airway wall and excessive mucus production." (PMID 41040870, 2025). "The Th2 subpopulation, which generates IL-4, IL-5, IL-9 and IL-13, contributes to asthma disease pathogenesis." (PMID 40095032, 2025). "ILC2 and Th2 cells secrete large amounts of type 2 cytokines (T2), IL-4, IL-5, and IL-13, which are key drivers of asthma pathogenesis." (PMID 40370530, 2025). "Dupilumab, a monoclonal antibody targeting interleukin-4 (IL-4) and IL-13, is widely used for the treatment of type 2 inflammatory conditions such as atopic dermatitis, asthma, and chronic rhinosinusitis with nasal polyposis." (PMID 40895907, 2025). "IL-5 inhibitors seemed to show a more pronounced increase in asthma control than IL-4/IL-13 inhibitors with MDs of −0.4 and −0.2, respectively." (PMID 39844912, 2025). "The elevated levels of IL‐4 and IL‐8 in asthma patients following dust storms agree with microbial alterations observed in our metagenomic profiling." (PMID 41185941, 2025). "A cytokine closely related to IgE is IL-4, a key cytokine in allergic diseases that mainly acts in the early stages of asthma and promotes the process of synthesizing IgE and replacing macrophages with M2 cells." (PMID 40958130, 2025). "Studies indicate that IL-4 and IL-13, key cytokines in asthma, disrupt TJ components, impairing barrier function in asthma." (PMID 41303221, 2025). "IL-4, another Th2-dominant cytokine in asthma, sharing a promiscuous receptor with IL-13, has overlapping effects on goblet cell hyperplasia; however, IL-13 dominates over the other one." (PMID 38339210, 2024). "Chronic exposure to IL-4 can even remodel the structure of the airways, increasing the persistent nature of asthma." (PMID 39407835, 2024). "In a proof-of-concept study, combined vaccination against IL-4 and IL-13 showed both prophylactic and therapeutic efficacy in a mouse model of asthma." (PMID 38609094, 2024). "Th2 cells, which predominate in allergic reactions and asthma, are the primary source of the type 2 cytokines IL-4, IL-5, and IL-13." (PMID 38731707, 2024).